TREM1 (triggering receptor expressed on myeloid cells 1)
Diseases named in the same sentence as TREM1 in open-access papers (continued):
Sharing a sentence is not in itself a finding about the gene and the disease.
cancer (continued). "Concerning the relationship of uPAR and TREM1 with the telomere system, one study showed that uPA (the ligand for uPAR) is positively associated with the TERT component of TE and that hTERT enhances uPA expression in cancer cells." (PMID 40149509, 2025). "We thus hypothesize that CD46/TREM1 may contribute to the inflammation-cancer transformation in OSCC by activating the PI3K-AKT-mTOR pathway and subsequently inhibiting autophagy, as indicated by downregulated LC3B/ATG5." (PMID 41415031, 2025). "The results showed that CD46 and TREM1 genes were overexpressed on the surface of cancer tissues." (PMID 40475017, 2025). "Enrichment analysis showed that TREM1 was highly enriched in cancer-and immune-related pathways." (PMID 39744496, 2025). "Finally, the expression, prognosis and immune regulation patterns of TREM1 in pan-cancer were further explored to validate the role of TREM1 as a biomarker." (PMID 39744496, 2025). "As suggested by prior work in other cancers, a direct physical interaction between TREM1 and TLR4 may underpin the observed signaling activation." (PMID 41394801, 2025). "Collectively, TREM1 was overexpressed in multiple cancer types." (PMID 39744496, 2025). "Combining TREM-1 inhibitors with other immune-modulating agents, such as cytokine blockers or checkpoint inhibitors, may offer new treatment possibilities for cancer and complex inflammatory disorders." (PMID 41226426, 2025). "Collectively, findings across these genetic models reveal that TREM-1 is a potent amplifier of innate immune responses and a driver of immunopathology, particularly in chronic inflammation, cardiovascular disease, infectious models, and cancer." (PMID 41226426, 2025). "They conclude that TREM-1 and the inflammatory response may play an important role in cancer progression." (PMID 40917508, 2025). "Researchers have intensively focused on TREM-1′s role in cancer diseases." (PMID 38541074, 2024). "In response to stimulation from cancer cells, the expression of the TREM-1 increases, promoting KCs activation and HCC progression, while TREM-1 deficiency has been found to decrease the release of IL-1β, IL-6, CCL2, and CXCL10 by KCs, resulting in suppressed HCC growth." (PMID 38229178, 2024). "The findings from our study illuminate the prevalent hypomethylation of TREM1 in multiple cancer types, coupled with increased gene expression levels, as evident from TCGA dataset analysis, suggesting a potential mechanism driving TREM1 dysregulation in tumorigenesis." (PMID 39149674, 2024). "We found that TREM1 gene expression is higher in various cancers while DNA methylation is lower." (PMID 39149674, 2024). "Accumulating results suggest that targeting TREM1 could be a promising therapeutic strategy for cancer treatment." (PMID 39149674, 2024). "However, TREM1 involvement in cancers and its correlation with DNA methylation levels remain uncertain." (PMID 39149674, 2024). "Currently, the crucial pathophysiological role of TREM1 is defined not only in infectious diseases such as sepsis but also in atherosclerosis, ischemia reperfusion–induced tissue injury, colitis, fibrosis, and cancer." (PMID 37651197, 2023). "In addition to a role of TREM1 expression on immune cells, there has been growing interest on the role of TREM1 as a driver of oncogenesis in cancer cells." (PMID 37651197, 2023). "We examined whether loss of TREM1 signaling can abrogate the immunosuppressive TME and enhance cancer immunity." (PMID 37651197, 2023). "Although the intrinsic role of TREM1 in cancer cells remains unclear, we have observed TREM1 expression in several human cancer cell lines, such as HepG2, Huh7, U87, and U251." (PMID 37651197, 2023). "TREM1 is currently extensively studied in cancer and inflammation." (PMID 36686646, 2022). "This may also contribute to the previous findings that TREM-1 expression in LC tumors is predictive for cancer aggressiveness and outcome." (PMID 33753779, 2021).
cancer (continued). "GEPIA showed that the TREM-1 expression status varied across cancers." (PMID 34122331, 2021). "To date, only a handful of studies have investigated roles for TREM-1 in cancer." (PMID 34956864, 2021). "Across individual tumors, we examined the frequencies and expression levels of TREM1 and its target genes in cancer cells and fibroblasts where sparse, yet moderate to high TREM1 expression could be detected in some cells." (PMID 34956864, 2021). "TREM1 has been reported to exert pro-inflammatory immune responses not only in acute pathogen-induced reactions but also in chronic and non-infectious inflammatory disorders, including various types of cancer." (PMID 32765489, 2020). "Recently, a phase I clinical trial has been run to evaluate the safety, tolerability, and pharmacokinetics of the synthetic peptide nangibotide (LR12), the first drug candidate targeting TREM-1 to reach clinical stage development, and future assessment of this agent for cancer therapy is expected." (PMID 32456204, 2020). "Several other studies support a role for TREM1 in the development of cancer." (PMID 32765489, 2020). "Considering the widely accepted connection between bowel inflammation and cancer, the pro-inflammatory activity of TREM-1 might have a role also in tumorigenesis." (PMID 31546668, 2019). "Thus, we investigated the role of TREM-1 on ApoE KO mice originated NK cell mediated cytotoxicity for cancer cells." (PMID 31275318, 2019). "Our data may further challenge the current notion that TREM-1+ macrophages may be the critical players across all types of cancer by identifying neutrophils as the major TREM-1-expressing cell subset in the AOM/DSS model of inflammation-induced CRC." (PMID 29093489, 2017). "Considering the well-established link between innate inflammation and cancer, TREM-1 may emerge as a powerful prognostic indicator not only in CRC but across several types of cancer." (PMID 29093489, 2017). "Furthermore, the proportion of TREM1+ PMN-MDSCs also varied markedly among these cancer types." (PMID 41413734, 2025). "Additionally, blocking TREM-1 activity suppresses the migration of HCC cells during the early stages of carcinogenesis, particularly in response to conditioned media (CM) from HSC-derived cancer-associated myofibroblasts (CAMFs)." (PMID 41226426, 2025). "Therefore, VJDT, as a TREM-1 inhibitor, shows promise as a novel cancer therapeutic agent." (PMID 41226426, 2025). "Importantly, our findings also demonstrated that TREM1 could serve as a potential target for cancer immunotherapy." (PMID 41413734, 2025). "However, the high expression of TREM1 in cancer mechanisms is still unclear." (PMID 39149674, 2024). "Similarly, we propose that the hypomethylation status of TREM1 could also serve as a potential biomarker for various cancers." (PMID 39149674, 2024). "Triggering receptor expression on myeloid cells-1 (TREM1) belongs to the immunoglobulin superfamily and is implicated in various conditions, including infectious and non-infectious diseases, autoimmune disorders, and cancer." (PMID 39149674, 2024). "Notably, TREM1 is significantly dysregulated in numerous cancer types." (PMID 39149674, 2024). "Moreover, targeting TREM1 could be a more effective therapeutic strategy for the treatment of various cancers." (PMID 39149674, 2024). "According to reports, TREM1 may serve as a prognostic factor for cancer prevention." (PMID 39187376, 2024). "In comparison to moderate-severe OED, immune signatures associated with poor cancer prognosis were further induced in early stage OSCC, such as immune checkpoint, IL-8 and TREM1 We speculate that a continuous induction of these genes may lead to immune evasion." (PMID 36119104, 2022). "For example, the TREM1 pathway could be beneficially associated with M1 tumoricidal macrophages, and the predicted inhibition of the PD1/PD-L1 cancer immunotherapy pathway in IL27-containing groups could act to enhance T cell activation, proliferation, and survival." (PMID 34209203, 2021).
cancer (continued). "In addition, Inhibition of TREM-1 by short hairpin RNA (shRNA) in macrophages could suppress cancer cell invasion in vitro." (PMID 27244892, 2016). "TREM1 in macrophages facilitates their transformation into the M1 subtype via the PI3K/AKT signaling pathway, thereby enhancing cancer cell invasiveness." (PMID 41394801, 2025). "Radar chart showing the connection between TREM1 expression and TMB was significant in eight cancer types, and the correlation with MSI was also reflected in four types of cancer." (PMID 39744496, 2025). "Significant canonical pathways included Molecular Mechanisms of Cancer, ILK Signaling, Integrin Signaling, RAC Signaling, and TREM1 Signaling." (PMID 38297314, 2024). "Conversely, TREM1 and IBSP exhibited primary expression in TAM and secondary expression in cancer cells." (PMID 39574472, 2024). "This is further recapitulated in ingenuity pathway analysis (IPA), as enriched terms to psPD represent several immune response pathways driven by TREM1, TNF, IFNG, IL1, and IL6 while PD was primarily demarcated by E2F-mediated cancer activity." (PMID 38049893, 2023). "More clinical studies are urgently needed to confirm TREM-1 (and TREM family) roles in the prognosis and the treatment of human cancer." (PMID 35875168, 2022). "Moreover, early studies in myeloid cells identified DAP12 as a receptor by showing that when ligated by TREM1 it can induce activation and inflammatory responses, particularly of neutrophils and macrophages and the changes in these DAP12 pathways are linked to cancer survival." (PMID 33513928, 2021). "In this study, we examined the expression of the pro-inflammatory receptor TREM-1 and the anti-inflammatory receptor TREM-2 on myeloid cells in the periphery and tumors of mice and patients with cancer." (PMID 35223446, 2021). "MDSC-secreted factors that overlap with TREM-1 target genes, including IL-1β, TNF-α, IL-8 and IL-6, have been reported to promote angiogenesis and induce cancer cell migration, invasion, and survival." (PMID 34956864, 2021). "However, in cancer biology, the role of TREM-1 is largely unknown." (PMID 31275318, 2019). "As to the underlying signaling pathways, HMGB1 receptors in HCC include RAGE, TLRs and TREM-1, though there are a number of receptors of HMGB1 in other cancers." (PMID 26393575, 2015). "Macrophages were transfected with siCOX-2 or control siRNA for 48 hours prior to co-culturing with cancer cells or normal epithelial cells (NL20) and expression of TREM-1 protein was detected by FACS analysis." (PMID 24842612, 2014). "Finally, univariate Cox regression analyses were utilized to elucidate correlation of TREM1 expression with OS and progression-free survival (PFS) of patients in TCGA pan-cancer." (PMID 39744496, 2025). "The immunohistochemistry results showed that the expression of CD46 and TREM1 in cancer tissues was significantly higher than that in normal mucosa and inflammatory tissues (P < 0.01)." (PMID 40475017, 2025). "These cells also expressed TREM1 and were enriched in PDAC, but absent in other cancers, suggesting a distinct PDAC-associated myeloid feature." (PMID 41228323, 2025). "Synergy of immunotherapy with macrophage-restricted, but not pan-TREM-1 blockade adds further evidence to support the conclusion on the various contributions of different myeloid cells to cancer progression." (PMID 41404075, 2025). "Considering the lack of TREM1-related cancer research, we explored the relevance of 18, 21our findings in 34 types of human common cancer from the TIMER2 database." (PMID 39744496, 2025). "Notably, in three representative cancer types—KIRC, LUSC and LGG—the high TREM1+ PMN-MDSCs infiltration group exhibited significantly higher scores for these features compared to the low-infiltration group." (PMID 41413734, 2025).
cancer (continued). "Furthermore, elevated TREM1 expression correlates significantly with poor prognosis in ESCA, HNSC, KIRC, KIRP, PAAD, and STAD cancers, as indicated by KM plot analysis, highlighting its potential as a prognostic marker." (PMID 39149674, 2024). "Accumulating evidence suggests that TREM1 plays a crucial role in chronic and non-infectious inflammatory disorders, including various types of cancer." (PMID 39149674, 2024). "Our study suggests that TREM1, MAPK1, MAPK8, CTSB, MIF, and DPP4 proteins may be targeted by compounds in medicinal plants for their anti-cancer effects." (PMID 37454152, 2023). "In that situation, we may notice that TREM-1 has mainly been studied in colon, hepatocellular and lung (NSCLC) carcinoma tissues that highly expressed TREM-1 (as well as sTREM-1)." (PMID 35875168, 2022). "In addition, TISIDB analysis suggested that TREM-1 expression was positively correlated with the levels of 28 TIL types and immunostimulators across human cancers and that these correlations were particularly significant in THCA." (PMID 34122331, 2021). "In contrast to myeloid cells, neither the cancer cell nor fibroblast compartments showed high frequency TREM1 expression in individual tumors or coordinated expression of target genes." (PMID 34956864, 2021). "A correlation of TREM-1 and the M2 state could explain why the beneficial purpose of TREM-1 in infectious disease gained an opposite role in cancer." (PMID 30018308, 2018). "It is speculated that CD46 and TREM1 may inhibit autophagic apoptotic genes LC3B and ATG5 by mediating the activation of the inflammatory cancer chain, thus weakening the apoptotic signal and leading to the proliferation and escape of cancer cells." (PMID 40475017, 2025). "Likewise, our research study revealed a negative correlation between TREM1 gene expression and DNA methylation across various cancers." (PMID 39149674, 2024). "Thus, targeting TREM1 to modify an immunosuppressive TME and improve efficacy of immune checkpoint therapy represents what we believe to be a promising therapeutic approach to cancer." (PMID 37651197, 2023). "Trem1 is a receptor expressed by innate immune cells, including macrophages, and it is reported to amplify the inflammatory response in infectious and non-infectious diseases, such as cancer." (PMID 36555441, 2022). "Furthermore, correlation analysis between TREM-1 expression and 28 types of TILs across human cancers revealed that TREM-1 may participate in complicated immune cell crosstalk, possibly explaining why TREM-1 is closely related to lymph node metastasis in PTC." (PMID 34122331, 2021). "In addition to infectious disease, recent evidence suggests TREM1 also plays a significant role in non-infectious diseases including cancer." (PMID 33664852, 2021). "In more rare instances we observed TREM-1 staining in non-myeloid cells of tumors (P3), such as moderate TREM-1 staining in cancer cells (n=2), or moderate to high TREM1 staining in cells morphologically consistent with cancer-associated fibroblasts (n=3)." (PMID 34956864, 2021).
infectious disease (33 papers, 2008 to 2026). A disorder directly resulting from the presence and activity of a microbial, viral, or parasitic agent in humans. "TREM-1 is a potent amplifier of the inflammatory response and is associated with infectious diseases." (PMID 32984356, 2020). "TREM-1 expression is increased in infectious diseases and is associated with the release of soluble TREM-1 (sTREM-1)." (PMID 21356122, 2011). "TREM1 is expressed on neutrophils, monocytes, and tissue macrophages and is implicated in the propagation/amplification of inflammation induced by stimulation of TLRs in the pathogenesis of many infectious diseases." (PMID 32391286, 2020). "Triggering receptor expressed on myeloid cells-1 (TREM-1) is a potent amplifier of inflammatory responses and plays a critical role in the pathogenesis of various infectious diseases." (PMID 41511954, 2026). "As an important amplifier of inflammatory responses, the role of TREM1 in infectious diseases and cardiovascular diseases has received extensive attention." (PMID 41511954, 2026). "As a transmembrane glycoprotein, TREM-1 is mainly expressed in endothelial cells, and monocytes/macrophages, and it is involved in both infectious and non-infectious diseases." (PMID 41451290, 2025). "In infectious diseases, the Triggering Receptor Expressed on Myeloid cells-1 (TREM-1) pathway is drawing increased attention." (PMID 37574520, 2023). "The literature indicates that soluble TREM-1 is an effective indicator to evaluate the severity and prognosis of infectious diseases." (PMID 37733081, 2023). "Nevertheless, recent extensive studies have found that sTREM-1 is a reliable biomarker for the diagnosis of infectious diseases, particularly in septic shock, and specifically indicates the TREM-1 pathway activation." (PMID 35487953, 2022). "Current evidence showed that TREM-1 appears to augment inflammatory responses in infectious diseases." (PMID 35637975, 2022). "In this review, we discuss the current understanding of the immunoregulatory functions of TREM-1 on acute infectious diseases and then highlight the crucial roles of TREM-1 on the development of STSLS." (PMID 29619033, 2018). "Here, we present the current progresses of the immunoregulatory functions of TREM-1 on acute infectious diseases and highlight the essential roles of TREM-1 on the development of STSLS." (PMID 29619033, 2018). "TREM-1 is an amplifier of inflammatory response, and is involved in the pathogenesis of many infectious diseases." (PMID 28004759, 2016). "The studies cited above confirmed that TREM-1 serves as an amplifier of inflammation and plays an important role in infectious disease." (PMID 25464008, 2014). "Several recent reports demonstrate an important role for TREM-1 in inflammation during an infectious disease; the receptor appears to act as an amplifier of the immune response in the presence of pathogens." (PMID 18628981, 2008). "High levels of soluble TREM-1 have been identified by others in patients suffering from diverse infectious diseases and in particular in their fluids." (PMID 18628981, 2008). "Although existing reviews on TREM-1 have provided valuable insights into its pathophysiological role across a broad spectrum of inflammatory and infectious diseases, as well as its inhibition through peptide-based approaches, they remain largely limited in scope." (PMID 41226426, 2025). "In addition, TREM-1 has been consistently investigated in inflammatory and infectious diseases, since its main function is to amplify inflammatory responses." (PMID 37626613, 2023). "TREM1 mainly expressed in myeloid lineage cells, especially in monocytes/macrophages, and it was involved in the innate immune response and amplified proinflammatory response in both infectious and non-infectious diseases." (PMID 34221733, 2021).